MYLK-AS1 (MYLK antisense RNA 1)
Synonyms: MYLK-AS2
Gene: Long non-coding RNA gene on chromosome 3 (123,584,354 to 123,716,399, forward strand). Ensembl gene ENSG00000239523.
Diseases named in the same sentence as MYLK-AS1 in open-access papers:
MYLK-AS1 is named in the same sentence as 3 diseases in open-access papers, as found by Europe PMC text mining. Sharing a sentence is not in itself a finding about the gene and the disease. The quoted sentences say what the papers report.
tumor (1 paper, 2020). "Consistently, MYLK-AS1 knockdown hinders tumor growth in vivo." (PMID 32398965, 2020).
MYLK-AS1 also shares sentences with these, for which no sentence is quoted: cancer (1 paper); colon adenocarcinoma (1).